H19 (H19 imprinted maternally expressed transcript)
Diseases named in the same sentence as H19 in open-access papers (continued):
Sharing a sentence is not in itself a finding about the gene and the disease.
pancreatic ductal adenocarcinoma (20 papers, 2010 to 2023). An infiltrating adenocarcinoma that arises from the epithelial cells of the pancreas. "Moreover, LncRNA H19 has a unique expression profile and can act as a sponger of specific miRNAs to regulate the pathogenic process of pancreatic ductal adenocarcinoma and several other types of cancer." (PMID 37175724, 2023). "For example, elevated H19 in pancreatic ductal adenocarcinoma can accelerate cell proliferation and migration of the tumor cells by negatively regulating miR-194." (PMID 37253635, 2023). "This H19/miR-194/PFTK1 axis modulated pancreatic ductal adenocarcinoma cell proliferation and migration through Wnt/β-catenin signaling by regulating the levels of phosphorylated LRP6 Snail and increasing phosphorylated β-catenin protein levels." (PMID 34977037, 2021). "H19 and PFTK1 are both upregulated in pancreatic ductal adenocarcinoma (PDAC) samples, and the association between H19 and PFTK1 was discovered along with the functional microRNA-194." (PMID 32042268, 2020). "LncRNA H19 was reported to be overexpressed in pancreatic ductal adenocarcinoma and plays oncogenic role through promoting cancer cell proliferation." (PMID 28187755, 2017). "Further support for the role of the H19/let-7/Hmg2 axis in the promotion of tumor metastasis was recently provided in a study of H19 in pancreatic ductal adenocarcinoma (PDAC)." (PMID 26623562, 2016). "H19 can also promote cell invasion and migration in pancreatic ductal adenocarcinoma, at least partially by increasing HMGA2-mediated epithelial-mesenchymal transition through antagonizing let-7." (PMID 25944697, 2015). "In addition, studies have shown that H19 enhances invasion and migration of pancreatic ductal adenocarcinoma cells by decreasing let-7 and subsequently increasing the HMGA2-mediated epithelial-mesenchymal transition (EMT)." (PMID 30071841, 2018). "Recently, researchers indicated that H19 inhibited endogenous let-7 function, causing derepression of HMGA2 which could mediate epithelial-mesenchymal transition (EMT) in pancreatic ductal adenocarcinoma (PDAC), and contributed to PDAC metastasis." (PMID 27672656, 2016). "For example, the levels of H19 was overexpressed in pancreatic ductal adenocarcinoma (PDAC)." (PMID 26376677, 2015). "H19 may be a novel therapeutic target for pancreatic ductal adenocarcinoma." (PMID 37175724, 2023). "Recently, we reported that H19 contributes to the metastasis of pancreatic ductal adenocarcinoma (PDAC) cells and that inhibition of H19 reduces metastasis in vivo." (PMID 30410672, 2018). "In 45 paired pancreatic ductal adenocarcinoma and noncancerous tissue samples, both H19 and PFTK1 were highly expressed and correlated with distant metastasis, advanced TNM stages, and overall survival." (PMID 34977037, 2021). "H19 could also act as a molecular sponge for let-7, which is a well-known tumor suppressor miRNA capable of targeting and inhibiting oncogenic HMGA2, a mediator of epithelial–mesenchymal transition (EMT) in pancreatic ductal adenocarcinoma (PDAC)." (PMID 33800276, 2021).
endometrial cancer (19 papers, 2015 to 2025). Primary or metastatic malignant neoplasm involving the endometrium (mucous membrane that lines the endometrial cavity). "In ovarian and endometrial cancer, the reciprocal functions of H19 and let-7 were associated with let-7-mediated regulation of metastasis-related genes, including c-Myc, HMGA2, and IGF2BP3." (PMID 27686732, 2016). "Similarly, elevated levels of H19 expression have been observed in endometrial cancer, and these high levels have been linked to increased cell growth potential." (PMID 38166752, 2024). "Few important Circulatory lncRNAs as biomarkers and their roles are as follows.H19: Elevated in ovarian and endometrial cancers, H19 correlates with tumor proliferation, metastasis, and chemoresistance." (PMID 39912983, 2025). "Studies have shown that H19 contributes to the progression of ovarian and endometrial cancer through various mechanisms, such as inducing epithelial to mesenchymal transition (EMT)." (PMID 38166752, 2024). "Conversely, in endometrial cancer, H19 acts as a tumor suppressor by inhibiting proliferation, inducing apoptosis, and regulating epithelial-mesenchymal transition." (PMID 38166752, 2024). "Another study has shown that H19 plays a role in the progression of endometrial cancer by affecting the EMT process." (PMID 38166752, 2024). "Metformin inhibits tumor cell invasion and migration partly by H19 downregulation and decreases the expression of H19 in Endometrial Cancer." (PMID 36849958, 2023). "In endometrial cancer, the lncRNA H19 has been shown to be significantly overexpressed in 60% of EC." (PMID 35054814, 2022). "H19 regulates the expression of its target gene HOXA10 in endometrial carcinoma by competing with miR-612." (PMID 34130625, 2021). "As shown in endometrial cancer cell lines, H19 is sponging miR-20b-5p which directly targets the 3′UTR of HIF-1α and thus inhibits HIF-1α expression." (PMID 32640630, 2020). "In endometrial carcinoma, H19 regulates the expression of the β5, β3, and α4 integrins, which presumably leads to enhanced motility and increased invasive potential of the cells." (PMID 30410672, 2018). "Together, these results suggest that metformin upregulates let-7 in endometrial cancer cells, resulting in H19 degradation." (PMID 27775072, 2017). "Impressively, these same metformin-induced H19 repression and gene methylation changes are also observed in human tumor samples derived from endometrial cancer patients treated with metformin." (PMID 27775072, 2017). "This metformin-induced H19 repression and alteration of gene methylation are recapitulated in endometrial cancer tissue samples obtained from patients treated with antidiabetic doses of metformin." (PMID 27775072, 2017). "In vivo studies have also shown the co-expressions of oncogenes and H19 in both primary human ovarian and endometrial cancers, confirming the H19/let-7-dependent regulation." (PMID 27664137, 2017). "Exposing endometrial cancer cells to metformin leads to global DNA methylation changes mediated through the H19/SAHH axis." (PMID 27775072, 2017). "In endometrial carcinoma, H19 levels are very high and increase still further with ongoing dedifferentiation of the tumour tissue." (PMID 26556343, 2015). "This suggests that H19 may be a suitable diagnostics biomarker and a potential therapeutic target for endometrial cancer." (PMID 35054814, 2022). "These lncRNA-mRNA-miRNA regulatory associations have been observed in many diseases, including endometrial cancer; lncRNA H19, for example, was reported to accelerate tumor formation in endometrial cancer by regulating HIF-1α/AXL signaling through competition for miR-20b-5p." (PMID 33584822, 2021). "Together, these results support the hypothesis that metformin-induced downregulation of H19 activates SAHH in human endometrial cancer cells." (PMID 27775072, 2017).
endometrial cancer (continued). "E2 seems to constitute an important linkage between expression of these lncRNAs and altered levels of sex hormones as it positively correlates with up-regulation of H19 and HOTAIR in endometrial carcinoma." (PMID 26556343, 2015). "H19 has not been well studied in endometrial cancer, but our data suggest H19 may be a novel marker for the more aggressive endometrial tumor subtypes." (PMID 26132201, 2015).
lung adenocarcinoma (19 papers, 2013 to 2025). A carcinoma that arises from the lung and is characterized by the presence of malignant glandular epithelial cells. "Increased H19 expression was negatively correlated with cisplatin response in lung adenocarcinoma patients, which was associated with increased cell growth and metastasis and a cell-cycle arrest." (PMID 34421359, 2021). "In lung adenocarcinoma, H19 is responsible for tumor progression by mediating methylation-dependent repression of CDH1 promoter." (PMID 38355574, 2024). "The effects of CDH1 and lncRNA H19 on EMT‐related factors in lung adenocarcinoma cell line A549 were further detected by immunofluorescence." (PMID 31317666, 2019). "We downloaded lncRNA H19 expression in multiple cancers from the TCGA database and found that compared with normal tissues, lncRNA H19 was highly expressed in tissues of lung adenocarcinoma." (PMID 31317666, 2019). "In order to investigate the effects of CDH1 and lncRNA H19 on the proliferation and apoptosis of lung adenocarcinoma cells, we transfected the previously constructed plasmids into A549 cells, followed by sphere‐forming assay, CCK‐8 assay and flow cytometry." (PMID 31317666, 2019). "The effects of CDH1/lncRNA H19 on the EMT‐related factors in lung adenocarcinoma cell line A549 were explored by Western blot analysis." (PMID 31317666, 2019). "In the current study, we observed the potential mechanisms, biological function and clinical feature of lncRNA H19 in lung adenocarcinoma." (PMID 27911863, 2017). "In summary, H19-mediated regulation of cisplatin resistance in human lung adenocarcinoma cells is demonstrated for the first time." (PMID 27911863, 2017). "The present study aimed to investigate the correlation of long non-coding RNA (lncRNA) H19 with cisplatin-resistance and clinical outcome in lung adenocarcinoma." (PMID 27911863, 2017). "Combined together, this research studies the potential of H19, taking it as a valid therapeutic target for the cisplatin resistance reversal in patients suffering from lung adenocarcinoma." (PMID 27911863, 2017). "Besides, the LncRNA H19 SNP rs217727 are related to advanced tumor status for lung adenocarcinoma with EGFR wild type." (PMID 36011604, 2022). "Studies of lung adenocarcinoma have reported that in vitro, lncRNA H19 silencing suppresses cell proliferation, sphere-forming ability, apoptosis, migration, and invasion and inhibits the epithelial-mesenchymal transition process, and in vivo, it also results in suppressed tumorigenicity." (PMID 33656053, 2021). "The aim of the current study is to investigate potential associations among Long Noncoding RNA (LncRNA) H19 single nucleotide polymorphism (SNP) and epidermal growth factor receptor (EGFR) phenotypes on the clinicopathological characteristics of lung adenocarcinoma (LADC)." (PMID 33799753, 2021). "Here, we tried to investigate whether lncRNA H19 or CDH1 methylation could affect the development of lung adenocarcinoma." (PMID 31317666, 2019). "We downloaded lncRNA H19 expression in lung adenocarcinoma from the Cancer Genome Atlas (TCGA) database and found that compared with normal control tissues, lncRNA H19 was highly expressed in tissues of lung adenocarcinoma." (PMID 31317666, 2019). "The results showed that compared with the normal lung cell line HFL1, among the lung adenocarcinoma cell lines, A549 cell line had the highest lncRNA H19 expression and the second lowest CDH1 expression (A549 cell line only slightly higher than PC9 cell line; P > .05)." (PMID 31317666, 2019). "H19 could potentially serve as a molecular marker to predict the clinical outcomes of lung adenocarcinoma patients." (PMID 27911863, 2017).
lung adenocarcinoma (continued). "Our study indicated that the siRNA H19 increasing the sensitivity of lung adenocarcinoma cells to cisplatin might be correlated with G0/G1 cell cycle arrest, apoptosis enhancement and migration." (PMID 27911863, 2017). "In lung adenocarcinoma, highly expressed H19 could serve as predictors for the poor prognosis." (PMID 31299871, 2019). "Furthermore, we found that silencing of lncRNA H19 could inhibit methylation of CDH1 promoter in lung adenocarcinoma." (PMID 31317666, 2019). "Herein, we conducted this study to explore the effects of lncRNA H19 and CDH1 on lung adenocarcinoma with the involvement of methylation of CDH1, with the hope to raise the life quality of patients with lung adenocarcinoma." (PMID 31317666, 2019). "One of the key findings of our study was that silencing of lncRNA H19, overexpression of CDH1 or reducing CDH1 methylation suppressed proliferation, migration and invasion, promoted apoptosis of lung adenocarcinoma A549 cells and inhibited the EMT." (PMID 31317666, 2019). "Then, the regulatory mechanisms of lncRNA H19 were detected mainly in concert with the treatment of overexpression of lncRNA H19, siRNA against lncRNA H19, overexpression of CDH1 and demethylating agent A‐5az in lung adenocarcinoma A549 cell." (PMID 31317666, 2019). "Taken together, this study demonstrates that silencing of lncRNA H19 inhibits EMT and proliferation while promoting apoptosis of lung adenocarcinoma cells by inhibiting methylation of CDH1 promoter." (PMID 31317666, 2019). "At first, we found that lncRNA H19 and methylation of CDH1 were highly expressed in lung adenocarcinoma tissues compared with the normal adjacent tissues, while CDH1 expression was reciprocal." (PMID 31317666, 2019). "The results exhibited that compared with the adjacent tissues, the expression of lncRNA H19 was significantly elevated and the mRNA expression of CDH1 was notably decreased in the lung adenocarcinoma tissues (P < .05)." (PMID 31317666, 2019). "Therefore, we consider that H19 may play a major role in overcoming acquired resistance to cisplatin as a novel epigenetic regulator in lung adenocarcinoma such as ERCC1, and sensitizing H19 might be an efficient therapeutic intervention in cisplatin resistance of lung adenocarcinoma." (PMID 27911863, 2017). "Both H19 and CDH1 methylation were upregulated in lung adenocarcinoma tissues." (PMID 38355574, 2024). "LncRNA H19 and methylation of CDH1 were highly expressed in lung adenocarcinoma tissues." (PMID 31317666, 2019). "It was concluded that silencing of lncRNA H19, overexpression of CDH1 or inhibition of CDH1 methylation could suppress migration and invasion of lung adenocarcinoma cells." (PMID 31317666, 2019). "For investigation into the effects of CDH1 and lncRNA H19 on the EMT process, we further performed scratch test and Transwell assay to ascertain whether silencing of lncRNA H19, overexpression of CDH1 or inhibition of CDH1 methylation could affect migration and invasion of lung adenocarcinoma cells." (PMID 31317666, 2019). "To conclude, the present study demonstrated that silencing of lncRNA H19 inhibited EMT and proliferation while promoting apoptosis of lung adenocarcinoma cells via inhibition of methylation of CDH1 promoter, which may provide a novel molecular target for treatment of lung adenocarcinoma." (PMID 31317666, 2019). "H19 has been shown to regulate miR-148b-3p and promote the expression of dimethylarginine dimethylaminohydrolase 1 (DDAH1) through negative feedback in lung adenocarcinoma cells resistant to gefitinib." (PMID 36188624, 2022).
steatosis (19 papers, 2017 to 2025). Increased lipid within the cytoplasm of cells. "When PLIN2, a member of the lipid droplet protein family, was inhibited, this was associated with a 548-fold increase in H19 levels accompanied by decreased liver TGs, suggesting a role for H19 in steatosis." (PMID 36203751, 2022). "The expression of H19 is augmented by fatty acids in hepatocytes and high-fat diet-induced fatty liver, with the overexpression of H19 promoting steatosis and enhancing lipid accumulation." (PMID 40259926, 2025). "Given the interaction between lncRNA H19, hnRNPA1 protein, PPARγ and miR-130a, it can be inferred that H19 is a crucial lncRNA in the development of fatty liver and steatosis." (PMID 39872125, 2024). "In the context of MASLD, expression of H19 was increased in steatosis induced by oleic acid and by a high fat diet (HFD) in a mouse model during progression of MASLD." (PMID 39872125, 2024). "In NAFLD animal and FFA-treated cell models, overexpression of lncRNA-H19 (H19) promotes steatosis and increases hepatic lipid accumulation and lipogenesis via the miR-130a/PPARγ axis." (PMID 37190114, 2023). "Although some LncRNAs, such as MALAT1, H19, and NEAT1, were previously associated with NAFLD, the association of others with steatosis and the positive effect of Ex-4 is being reported for the first time." (PMID 34078383, 2021). "As a result of the interplay between lncRNA H19, hnRNPA1 protein, PPARγ, and miR-130a, it can be concluded that H19 is one of the most important lncRNAs in the formation of fatty liver and steatosis." (PMID 33622377, 2021). "One study found that overexpression of H19 prevented the development of steatosis, however other studies have shown that overexpression of H19 induced steatosis." (PMID 33115498, 2020). "We found that H19 was up‐regulated in oleic acid‐induced steatosis and during the development of high‐fat diet (HFD)‐induced NAFLD." (PMID 31809000, 2020). "These authors observed increased expression of H19 in steatosis and high-fat diet (HFD)-induced fatty liver." (PMID 32429417, 2020). "Vice versa, H19 is induced by fatty acids in hepatocytes, and ectopic expression of H19 induces steatosis." (PMID 32429417, 2020). "Further, transgenic overexpression of the IGF2 mRNA binding protein (IGF2BP2/IMP2), leading to upregulated expression of H19, induces steatosis and promotes NASH progression." (PMID 32429417, 2020). "In summary, we demonstrated that elevated H19 expression is a characteristic molecular change in NAFLD, and H19 promotes hepatocyte steatosis, TG secretion and expression of NAFLD-related genes via activating PPARγ signal by sponging miR-130a." (PMID 31064820, 2019). "Ectopic expression of H19 induced steatosis and pushed the liver into a “pseudo fed” state in response to fasting by promoting PTBP1-mediated SREBP1c protein cleavage and nuclear translocation." (PMID 30148159, 2017). "Another study links H19 to steatosis through PLIN2, a member of the lipid droplet protein family that is markedly increased in fatty liver." (PMID 28933364, 2017). "Moreover, the overexpression of H19 contributes to the downregulation of pro-osteogenic genes promotes steatosis, and augments lipid accumulation." (PMID 40259926, 2025). "Additionally, miR-130a expression was associated with downregulation of the lipogenesis genes Fasn, Acc, Srebp1 and Scd1; therefore, the inhibitory action of H19 on miR-130a promoted steatosis." (PMID 39872125, 2024). "In addition, HuR was found to be a repressor of H19, a long non-coding RNA reported to modulate hepatic metabolic homeostasis in NAFLD, whose overexpression is associated with steatosis and the development of obstructive cholestatic liver fibrosis." (PMID 37372956, 2023). "Steatosis and NAFLD caused by a high-fat diet (HFD) increased H19 expression." (PMID 36552725, 2022).